SNORD61 (small nucleolar RNA, C/D box 61)
Synonyms: U61; HBII-342; RNU61
Gene: Small nucleolar RNA gene on chromosome X (136,879,199 to 136,879,271, reverse strand). Ensembl gene ENSG00000206979.
Gene Ontology:
Biological process: RNA processing
Cellular component: nucleolus
Homologues: Orthologues: chimpanzee SNORD61 (99% identical), macaque SNORD61 (99% identical), pig SNORD61 (90% identical), rabbit SNORD61 (90% identical), rat Snord61 (86% identical), mouse Snord61 (82% identical).